ABCA13 (ATP binding cassette subfamily A member 13)
Description:
May mediate the cholesterol and gangliosides transport from the plasma membrane to intracellular vesicles in an ATP hydrolysis dependent manner, thus playing a role in their internalization by endocytic retrograde transport and may also participate in the endocytosis of synaptic vesicle in cortical neurons.
Synonyms: FLJ33876; FLJ33951
Tractability: Small molecule: it belongs to a druggable protein family. Antibody: its Gene Ontology location is reachable by antibodies, with high confidence; UniProt predicts a signal peptide or a membrane-spanning region.
Gene: Protein-coding gene on chromosome 7 (48,171,458 to 48,647,497, forward strand). Ensembl gene ENSG00000179869.
Subcellular location: Cytoplasmic vesicle membrane
Subcellular location (Human Protein Atlas): Nucleoplasm; Vesicles; Basal body; Centrosome; Cytosol
Pathways (Reactome):
Immune System: Neutrophil degranulation
Gene Ontology:
Molecular function: ATPase-coupled transmembrane transporter activity; ABC-type transporter activity; ATP binding; ATP hydrolysis activity
Biological process: positive regulation of cholesterol transport; ceramide transport; positive regulation of synaptic vesicle endocytosis; transmembrane transport
Cellular component: cytoplasmic vesicle membrane; intracellular vesicle; azurophil granule membrane; plasma membrane; secretory granule membrane; membrane
Genetic constraint (gnomAD): Loss-of-function variants: 420 observed, 428.26 expected, observed/expected ratio (o/e) 0.98, 90% interval 0.9 to 1.06. The upper end of that interval is the gene's LOEUF score, 1.06, which puts it in group 4 of 6, group 1 being the genes least tolerant of losing a copy. Missense variants: 5,843 observed, 5,822.6 expected, observed/expected ratio (o/e) 1, 90% interval 0.98 to 1.02. Synonymous variants: 2,181 observed, 2,146.9 expected, observed/expected ratio (o/e) 1.02, 90% interval 0.98 to 1.05.
Homologues: Orthologues: chimpanzee ABCA13 (98% identical), macaque ABCA13 (92% identical), mouse Abca13 (66% identical), rat Abca13 (65% identical), pig ABCA13 (62% identical), Caenorhabditis elegans abt-2 (10% identical), Caenorhabditis elegans abt-4 (10% identical), Drosophila melanogaster ldd (10% identical), Drosophila melanogaster Abca3 (9% identical), Drosophila melanogaster CG6052 (9% identical), zebrafish abca5 (8% identical), Drosophila melanogaster CG31213 (8% identical), and 7 more. Paralogues in human: ABCA12 (18% identical), ABCA1 (14% identical), ABCA4 (14% identical), ABCA7 (13% identical), ABCA2 (13% identical), ABCA3 (10% identical), ABCA6 (8% identical), ABCA5 (8% identical), ABCA8 (8% identical), ABCA9 (8% identical), ABCA10 (8% identical).
Diseases named in the same sentence as ABCA13 in open-access papers:
ABCA13 is named in the same sentence as 48 diseases in open-access papers, as found by Europe PMC text mining. Sharing a sentence is not in itself a finding about the gene and the disease. The quoted sentences say what the papers report.
schizophrenia (11 papers, 2016 to 2023). A major psychotic disorder characterized by abnormalities in the perception or expression of reality. "From the viewpoint of human genetics studies, although ABCA13 harbors a relatively large number of LoF variants (pLI = 0), researchers have suggested that SNVs in ABCA13 confer susceptibility to neuropsychiatric disorders, including schizophrenia and ASD." (PMID 35811316, 2022). "Previous studies have suggested that rare coding variants of human ABCA13 contribute to the risk of schizophrenia, bipolar disorder, and major depression." (PMID 33478937, 2021). "Rare genetic variants of human ABCA13 were reported to increase the susceptibility to schizophrenia, bipolar disorder, and major depression." (PMID 33478937, 2021). "Mutations in the ABCA13 gene were reported to increase the susceptibility to schizophrenia, bipolar disorder, and major depression." (PMID 33478937, 2021). "The three missense mutations in ABCA13 we investigated (H3609P, T4031A, and R4843C) were selected because they increase the susceptibility to schizophrenia and bipolar disorder." (PMID 33478937, 2021). "The ABCA8 gene is important for lipid metabolism in oligodendrocytes, myelin formation and maintenance, and ABCA13 from the same subfamily is associated to schizophrenia through GWAS." (PMID 33892787, 2021). "They found that rs17132388 and rs6583476 of ABCA13 show a statistically significant association with schizophrenia." (PMID 33299069, 2020). "The objective of this study was to investigate the expression and clinical role of ATP-binding cassette transporter 13 (ABCA13) gene previously shown to be associated with schizophrenia (SZ) through Genome-wide association studies studies." (PMID 33299069, 2020). "Considering the interactions between rare and common variants, further genetic and functional studies of ABCA13 are necessary to elucidate its possible role in schizophrenia." (PMID 33299069, 2020). "ABCA13 is responsible for lipid transport and variants in this gene can cause schizophrenia." (PMID 33334016, 2020). "In addition to rare genetic variants, some researchers have also explored the relationship between common genetic variants in ABCA13 and the pathogenesis of schizophrenia." (PMID 33299069, 2020). "Abca13 was also found to be associated with both schizophrenia and bipolar disorder." (PMID 27699085, 2016). "Additionally, both schizophrenia and bipolar disorder were associated with ABCA13 high expression." (PMID 34818212, 2021). "ABCA13 gene may contain genetic risk factors for schizophrenia in the Han Chinese population." (PMID 33299069, 2020). "ABCA13 has been studied mainly in terms of mental conditions, such as schizophrenia, bipolar disorder or depression." (PMID 36385764, 2022). "We found that ABCA13 mRNA levels were significantly lower in schizophrenia patients compared with healthy controls at baseline." (PMID 33299069, 2020). "Down-regulation of ABCA13 expression affects lipid metabolism and leads to abnormal lipid metabolism in patients with schizophrenia." (PMID 33299069, 2020). "Interestingly, rare genetic variants of human ABCA13 are related to susceptibility for schizophrenia, bipolar disorder, and major depression, but not without controversy." (PMID 33478937, 2021).
colorectal cancer (8 papers, 2010 to 2025). A primary or metastatic malignant neoplasm that affects the colon or rectum. "For instance, ABCA13 is a lipid transporter whose up-regulation has been associated with a better response to chemotherapy in breast cancer, as well as with longer disease-free survival after chemotherapy in colorectal cancer patients." (PMID 40332279, 2025). "A decreased expression of ABCA13 was associated with shorter DFS in 51 glioblastoma patients and 51 colorectal cancer patients." (PMID 33334016, 2020). "In humans, the expression of ABCA13 is elevated in subjects with several pathologies as leukemia, prostate tumor, colorectal cancer, and tumor cell lines in central nervous system." (PMID 32881863, 2020). "ABCA13 was found to be upregulated in colorectal cancer, and its high expression was related to less overall survival in metastatic ovarian serous carcinoma." (PMID 28378523, 2017). "The expression of Abca13 is elevated in leukemia, prostate tumor, colorectal cancer, and tumor cell lines in central nervous system." (PMID 27699085, 2016). "The enriched pathways included the Wnt signaling pathway (for somatic mutated gene DST eQTL), colorectal cancer (for somatic mutated gene FN1 eQTL) and Gap junction (for LOH mutated gene ABCA13 eQTL) with P-values 0.018, 0.012 and 0.013, respectively." (PMID 21114830, 2010).
bipolar disorder (7 papers, 2016 to 2025). A disorder of the brain that causes unusual shifts in mood, energy, activity levels and the ability to carry out day-to-day tasks. "For example, compound heterozygous ABCA13 variants p.(His3609Pro) and p.(Thr4550Ala) were correlated with the phenotype in three patients suffering from bipolar disorder." (PMID 40430072, 2025).
breast carcinoma (6 papers, 2015 to 2025). "A total of 16 genes were identified to be related to radiotherapy response, and low expression of SVOPL, EDAR, GSTA1, and ABCA13 was associated with poor overall survival and progression-free survival in breast cancer cases." (PMID 36896338, 2023). "The frequency of patients with mutations in ABCA13 was about threefold higher compared with post-menopausal ER+ breast cancer tumours from TCGA8." (PMID 27827358, 2016). "Moreover, univariate cox analysis indicated that only four of them (SVOPL, EDAR, GSTA1, and ABCA13) were associated with the overall survival (OS) of breast cancer patients." (PMID 36896338, 2023). "In conclusion, we identified that SVOPL, EDAR, GSTA1, and ABCA13 are potential prognostic biomarkers of patients with breast cancer undergoing chemoradiotherapy." (PMID 36896338, 2023). "An association has been found between ATP-binding cassette transporter genes like ABCA13 and outcome in breast cancer patients, most likely due to their role in drug resistance." (PMID 29293529, 2018).
major depression (5 papers, 2020 to 2023). "Knight and colleagues were the first to report the significant association of rare mutations of ABCA13 with SZ, BD, and major depression." (PMID 34947986, 2021). "The detection of the M4554I mutation of ABCA13 in this study agrees with the findings from Knight and colleagues and supports the proposal that rare mutations of ABCA13 might be involved in the pathogenesis of SZ, BD, and major depression." (PMID 34947986, 2021).
autism spectrum disorder (4 papers, 2020 to 2022). A spectrum of developmental disorders that includes autism, and Asperger syndrome. "In a recent study, ABCA13 was shown to be associated with synaptic function in autism spectrum disorder." (PMID 36385764, 2022). "A monkey carrying the heterozygous ABCA13 deletion displayed impaired social ability and restricted and repetitive behaviors that are most frequently associated with autism spectrum disorder." (PMID 33478937, 2021). "5-Hydroxytryptamine receptor 2C has been associated with neuropsychiatric disorders including autism spectrum disorder, leaving it unclear whether the heterozygous ABCA13 deletion caused the autism spectrum disorder-like phenotypes." (PMID 33478937, 2021). "Six AA individuals contain rare recurrent frameshift variants at exon 3 and 62 for ABCA13, which were annotated as ADHD-related genes by Genecards and is identified as overlapping gene for ADHD and Autism Spectrum Disorder (ASD) based on copy number variation analysis." (PMID 33671795, 2021).
gastric cancer (4 papers, 2016 to 2021). A primary or metastatic malignant neoplasm involving the stomach. "Thus, further analysis should concentrate on the collection of large-scale nucleotide polymorphism data to validate the prognostic value of ABCA13 in gastric cancer and the underlying regulatory interactions with lncRNA LINC2826, AC25575.2, and AFAP-AS1." (PMID 34728653, 2021). "ABCA13 is also considered a useful marker for predicting lymph node metastasis in resected gastric cancer patients in early stage." (PMID 32881863, 2020). "In a previous study, performed by array-Comparative Genomic Hybridization, we described for the first time in literature recurrent amplification of RTEL1 and ABCA13 genes in gastric cancer." (PMID 27366209, 2016). "Lastly, RTEL1 and ABCA13 synergistic effect may be considered as a putative marker for advanced staging in gastric cancer patients." (PMID 27366209, 2016). "ABCA13 amplification may have age-specific function and could be considered a useful marker for predicting lymph node metastasis in resected gastric cancer patients in early stage." (PMID 27366209, 2016). "Since men are more exposed to carcinogens than woman, the influx of carcinogenic substances by ABCA13 channel could explain the high frequency of amplification of this gene in male gender related to gastric cancer." (PMID 27366209, 2016). "Moreover, ABCA13 amplification may have age-specific function and could be considered a useful marker for predicting lymph node metastasis in resected gastric cancer patients in early stage." (PMID 27366209, 2016). "Survival analysis of subtype C2 shows that ABCA13, VPS13D, and CUBN affect the survival of gastric cancer." (PMID 34728653, 2021). "Other identified antigens have been correlated to other types of cancer, namely ABCA13 in ovarian cancer, XIRP2 in gastric cancer, and APOC2 expression in Non-Small Cell Lung Cancer." (PMID 32245227, 2020).
glioblastoma (3 papers, 2020 to 2023). The most malignant astrocytic tumor (WHO grade IV). "In the overlap analysis, we found the overexpression of ABCA13, PEG3, and SOX4 that have been shown to be poor prognostic markers in other cancers including ovarian, glioblastoma, and colon." (PMID 37370820, 2023).
leukemia (3 papers, 2016 to 2024). A malignant (clonal) hematologic disorder, involving hematopoietic stem cells and characterized by the presence of primitive or atypical myeloid or lymphoid cells in the bone marrow and the blood. "Of the upregulated genes, Syne1, Atxn10 and Dach1 show activation as early as Day 11, while Ngp, Abca13, Adpgk, Mmp8 and Lcn2 were more significantly upregulated in the later stage, D14 neutrophils,which suggests a sequential activation in Camk1d + neutrophils during leukemia progression." (PMID 38730491, 2024).
lymph node metastasis (3 papers, 2016 to 2024). "Previous studies have indicated that ABCA13 amplification increases the risk of lymph node metastasis and is associated with poor outcomes." (PMID 39671267, 2024). "Statistical analysis demonstrated that RTEL amplification is more common in older patients and more associated with intestinal type and ABCA13 amplification increases the risk of lymph node metastasis and is more common in men." (PMID 27366209, 2016). "Statistical analysis showed that ABCA13 amplification increases 3 times the risk of lymph node metastasis (p = 0.033; 95 % CI = 1.057–9.018)." (PMID 27366209, 2016). "Therefore, we suggest that amplification of ABCA13 gene has an important role in development of lymph node metastasis, which is associated with poor outcomes." (PMID 27366209, 2016).
ovarian carcinoma (3 papers, 2017 to 2020). A malignant neoplasm originating from the surface ovarian epithelium. "A recent study showed an association between higher ABCA13 levels and primary drug resistance, resulting in poor overall survival in ovarian cancer patients." (PMID 28978010, 2017). "The opposite was found for ovarian cancer (n = 77) and higher levels of ABCA13 predicted worse overall survival in ovarian cancer patients." (PMID 33334016, 2020).
Anxiety (2 papers, 2021 to 2023). Intense feelings of nervousness, tension, or panic often arise in response to interpersonal stresses. "Furthermore, we found that the body weight and behavioral phenotypes except for the prepulse inhibition of Abca13 KO mice were normal, indicating that the dysfunction of prepulse inhibition was not due to changes in body weight, motor function, activity, or anxiety levels." (PMID 33478937, 2021).
asthma (2 papers, 2019 to 2024). "Although changes in ABCA13 gene expression associate with both cigarette smoking and asthma status, unique changes in ABC transporter expression profiles are observed in samples isolated from asthmatics." (PMID 30655622, 2019). "The regulation of ABCA1 and ABCA13 is impacted by exposure to cigarette smoke, with ABCA13 expression showing differential expression in patients diagnosed with COPD and asthma." (PMID 38731891, 2024).
atherosclerosis (2 papers, 2015 to 2023). A disease characterized by the build-up of fatty material and calcium deposition in the arterial wall resulting in partial or complete occlusion of the arterial lumen. "The ABCA13 mutation may be linked with COPD along with atherosclerosis." (PMID 37447386, 2023).
glioma (2 papers, 2018 to 2023). A benign or malignant brain and spinal cord tumor that arises from glial cells (astrocytes, oligodendrocytes, ependymal cells). "The glioma, Wnt signaling pathways, renal cell carcinoma, VEGF signaling pathway, basal cell carcinoma, small cell lung cancer, melanogenesis, and ERBB signaling pathway were significantly enriched in the ABCA13 high-expressed phenotype." (PMID 36896338, 2023).
ischemic stroke (1 paper, 2016). A stroke disorder caused by obstruction of blood flow to the brain, due to thrombotic (local blood clot formation) or embolic (due to a blood clot or other material traveling from another site) event. "Taken together, the data suggest that Abca13 and Grb2 may be more important in ischemic stroke after hUC-MSC transplantation." (PMID 27699085, 2016).
lipid metabolism disorder (1 paper, 2023). "ABCA13 is involved in maintaining cellular lipid homeostasis by moving lipids inside the cell and in its plasma membrane, as well as removing lipids from the cells, and its mutation can induce a lipid metabolism disorder." (PMID 37447386, 2023).
neuroblastoma (1 paper, 2025). Neuroblastoma (NB) is the most common solid, extracranial childhood tumor. "We observed that both ABCA13 and LRP1B are expressed at higher levels in MYCN non-amplified neuroblastoma, a subgroup typically associated with less heterogeneous outcomes." (PMID 40599792, 2025).
oral squamous cell carcinoma (1 paper, 2016). "Regarding oral squamous cell carcinoma, we observed 30 and 25 % of RTEL1 and ABCA13 amplification, respectively, but the presence of amplification was not statistically associated with clinicopathological data of patients." (PMID 27366209, 2016).
osteosarcoma (1 paper, 2021). A usually aggressive malignant bone-forming mesenchymal neoplasm, predominantly affecting adolescents and young adults. "To examine whether human endogenous ABCA13 is localized in intracellular vesicles and affects intracellular cholesterol distribution, we used U2OS cells, a human osteosarcoma cell line that expresses endogenous ABCA13." (PMID 33478937, 2021).
Pasteurella multocida infection (1 paper, 2023). "It was also found that P0910 and ΔOmpH in Pasteurella multocida infection activated the expression of ropE, HSPBP1, FERH, ATP10A, ABCA13, RRP7A, IL-10, IFN-γ, IL-17A, EGFR and dnaJ." (PMID 36977260, 2023).
prostate carcinoma (1 paper, 2021). A carcinoma that arises from epithelial cells of the prostate gland. "High expression of ABCA13 has been demonstrated in prostate cancer, leukemia colorectal cancer, as well as several tumor cell lines in central nervous system." (PMID 34818212, 2021).
Stroke (1 paper, 2016). Sudden impairment of blood flow to a part of the brain due to occlusion or rupture of an artery to the brain. "There has been no previous report of Abca13’s involvement in stroke." (PMID 27699085, 2016).
thrombosis (1 paper, 2024). "Among them, mutations in ABCA13, FLT1, NRP1, SWAP70 and SLC15A4 are strongly associated with immunity or proliferation, whereas mutations in VWF, SELP and EPHB2 are associated mainly with thrombosis." (PMID 39671267, 2024). "On the other hand, SLE, like PNH, is characterised by complement activation and thrombogenesis, which can explain, to some extent, our finding that patients with thrombosis are likely to have higher SLC15A4 or ABCA13 mutation incidence than patients without thrombosis." (PMID 39671267, 2024). "In addition, we found that a greater proportion of patients with thrombosis than patients without thrombosis carried EpHB2 mutations (p = 0.015), SWAP70 mutations (p = 0.039), ABCA13 mutations (p = 0.01) and SLC15A4 mutations (p = 0.004)." (PMID 39671267, 2024).